TMEM240 (transmembrane protein 240)
Diseases named in the same sentence as TMEM240 in open-access papers:
TMEM240 is named in the same sentence as 33 diseases in open-access papers, as found by Europe PMC text mining. Sharing a sentence is not in itself a finding about the gene and the disease. The quoted sentences say what the papers report.
colorectal cancer (3 papers, 2020 to 2025). A primary or metastatic malignant neoplasm that affects the colon or rectum. "Low expression of the TMEM240 protein has been observed in about half of patients with inflammatory bowel diseases, which have a three to five times higher risk of developing colorectal cancer." (PMID 34638449, 2021). "The study’s results showed that hypermethylation and low expression of TMEM240 are potential biomarkers for colorectal cancer detection, poor prognosis, and early recurrence prediction." (PMID 34638449, 2021). "Transient transfection and knockdown of TMEM240 were performed to demonstrate the role of TMEM240 in colorectal cancer cells." (PMID 32398064, 2020). "Highly methylated CpG sites were identified in the TMEM240 gene by Illumina methylation 450K arrays in 26 Taiwanese patient paired samples and 38 paired samples from The Cancer Genome Atlas (TCGA) colorectal cancer dataset." (PMID 32398064, 2020). "Circulating cell-free methylated TMEM240 was detected in 13 of 25 (52.0%) Taiwanese colorectal cancer patients but in fewer (28.6%) healthy controls." (PMID 32398064, 2020). "Hypermethylation of TMEM240 has also been observed in colorectal cancer." (PMID 40691650, 2025). "Additionally, hypermethylation of TMEM240 has been shown to lead to the proliferation of breast cancer and colorectal cancer cells." (PMID 40691650, 2025). "Alterations in TMEM240 are commonly found in Western and Asian populations and can potentially be used for early prediction and as poor prognosis and early-recurrence biomarkers in colorectal cancer." (PMID 32398064, 2020).
spinocerebellar ataxia (3 papers, 2016 to 2024). "TMEM240 mutation should be included in the differential diagnosis of myoclonic dystonia and ataxia-dystonia syndromes." (PMID 38617829, 2024).
breast carcinoma (2 papers, 2022 to 2025). "In this study, we demonstrated that circulating methylated GCM2 and TMEM240 provide high diagnostic accuracy, sensitivity, and specificity for monitoring breast cancer progression." (PMID 40691650, 2025). "TMEM240 expression induces breast cancer cell death and enhances the cellular response to hormone therapy drugs, suggesting that deficiency in TMEM240 expression plays an important role during cancer progression in breast cancer patients." (PMID 35715741, 2022). "Deficiency in TMEM240 expression plays an important role during cancer progression in breast cancer patients." (PMID 35715741, 2022). "Combining measurement of TMEM240 hypermethylation with the measurement of additional breast cancer-specific methylated DNA biomarkers that are associated with disease progression will improve detection sensitivity and cancer specificity." (PMID 35715741, 2022). "Hypermethylation of TMEM240 in breast cancer was associated with poor response to hormone therapy in the TCGA cohort." (PMID 35715741, 2022). "Additionally, analysis of data from Taiwanese individuals in the TCGA database revealed that hypermethylation of transmembrane protein 240 (TMEM240) is associated with poor hormone therapy response in patients with breast cancer." (PMID 40691650, 2025). "Whether circulating methylated TMEM240 can be detected in blood from individuals with breast cancer and its association with treatment response and disease progression will also be investigated." (PMID 35715741, 2022). "Alterations in TMEM240 in female cancer are less frequent than those that occur in gastrointestinal cancer, but they are associated with poor clinical treatment response and poor prognosis in breast cancer." (PMID 35715741, 2022). "The plasma of patient H223 demonstrated increases in the abnormal methylation levels of circulating GCM2 and TMEM240 as her breast cancer progressed and decreases when the patients receive adequate treatment." (PMID 40691650, 2025). "This study investigates the potential of circulating methylated GCM2 and TMEM240 as biomarkers for noninvasive monitoring of breast cancer progression." (PMID 40691650, 2025). "Overall, detecting methylated GCM2 and TMEM240 in plasma offers a novel, accurate, and noninvasive method for monitoring breast cancer progression." (PMID 40691650, 2025). "To assess the cutoff value for detecting circulating methylated GCM2 and TMEM240 in plasma for predicting tumor progression, we employed a training group comprising 14 Eastern European and 152 Taiwanese breast cancer patients." (PMID 40691650, 2025). "Alterations in TMEM240 in breast cancer were identified and investigated to monitor treatment response and disease progression." (PMID 35715741, 2022). "We further analyzed the methylation patterns of TMEM240 in paired 101 Taiwan breast cancer patients, the methylation level of TMEM240 was at least twofold higher in 54.5% (55/101) breast tumor tissues than in the matched normal breast tissues." (PMID 35715741, 2022). "QMSP revealed that in 54.5% (55/101) of Taiwanese breast cancer patients, the methylation level of TMEM240 was at least twofold higher in tumor tissues than in matched normal breast tissues." (PMID 35715741, 2022). "A cell model showed that TMEM240, which is localized to the cell membrane and cytoplasm, represses breast cancer cell proliferation and migration and regulates the expression levels of enzymes involved in estrone and estradiol metabolism." (PMID 35715741, 2022). "The level of circulating methylated TMEM240 dramatically and gradually decreased in breast cancer patients following treatment (Case 1 and Case 2)." (PMID 35715741, 2022). "Circulating methylated TMEM240 in the plasma of breast cancer patients was used to monitor treatment response and disease progression." (PMID 35715741, 2022). "Hypermethylation of TMEM240 is a potential biomarker for treatment response and disease progression monitoring in breast cancer." (PMID 35715741, 2022).
breast carcinoma (continued). "Aberrant methylated TMEM240 was identified in breast cancer patients with poor hormone therapy response using genome-wide methylation analysis in the Taiwan and TCGA breast cancer cohorts." (PMID 35715741, 2022). "Methylation of TMEM240 was further analyzed in the TCGA cohort, and the gene was found to be highly methylated in breast cancer, endometrial and uterine cancer." (PMID 35715741, 2022). "Here, we further analyzed a TCGA cohort and found high methylation of TMEM240 in breast cancer and in endometrial and uterine cancer." (PMID 35715741, 2022). "Additionally, the methylation levels of GCM2 and TMEM240 can also reflect the treatment status of breast cancer patients in real time." (PMID 40691650, 2025). "Therefore, this study aimed to evaluate the potential of the simultaneous plasma detection of methylated GCM2 and TMEM240 in improving the prediction of residual disease and tumor progression in breast cancer patients." (PMID 40691650, 2025). "TMEM240 reveals the tumor suppressor potential for breast cancer cell growth and migration." (PMID 35715741, 2022). "Low expression of TMEM240 protein was observed in breast cancer patients." (PMID 35715741, 2022). "Low expression of TMEM240 protein was found in most Taiwanese and Korean breast cancer patients." (PMID 35715741, 2022). "Few reports are available regarding TMEM240 in women with cancer, and the role of TMEM240 in breast cancer remains unclear." (PMID 35715741, 2022). "We analyzed TMEM240 mRNA expression in 52 paired Taiwanese breast cancer tissues." (PMID 35715741, 2022). "In addition, the level of circulating methylated TMEM240 in plasma increased further in breast cancer patients with recurrence or metastasis." (PMID 35715741, 2022). "TMEM240 gene manipulation, viability, migration assays, RNA-seq, and MetaCore were performed to determine its biological functions and relationship to hormone drug treatment response in breast cancer cells." (PMID 35715741, 2022). "Analysis of RNA sequencing data from TCGA showed that TMEM240 mRNA expression was reduced by half in 51.4% (37/72) of the breast cancer tumor tissues compared with the matched normal breast tissues (p = 0.019) and in 60.2% (458/761) of tumors from breast cancer patients." (PMID 35715741, 2022). "Therefore, the CNVs of TMEM240 were investigated in breast cancer." (PMID 35715741, 2022). "We investigated whether TMEM240 mRNA was also expressed at lower levels in breast cancer." (PMID 35715741, 2022). "Therefore, TMEM240 in breast cancer was selected for further analysis." (PMID 35715741, 2022). "We hypothesized that tumor burden in breast cancer patients could be dynamically assessed by monitoring circulating methylated GCM2 and TMEM240 following treatment." (PMID 40691650, 2025). "Circulating methylated TMEM240 dramatically and gradually decreased and then diminished in blood of breast cancer patients without disease progression, whereas it increased in blood of breast cancer patients with recurrence or metastasis." (PMID 35715741, 2022). "Previously reported findings have indicated that circulating methylated TMEM240 levels gradually decrease in Taiwanese patients with nonprogressive breast cancer and increase in those with disease progression, demonstrating a remarkable predictive accuracy of 96.1%." (PMID 40691650, 2025). "Circulating methylated TMEM240 dramatically and gradually decreases and then diminishes in patients with various subtypes of breast cancer who do not show disease progression, suggesting that measurement of circulating methylated TMEM240 could be used to detect the presence of residual disease." (PMID 35715741, 2022).
esophageal cancer (2 papers, 2020 to 2022). A primary or metastatic malignant neoplasm involving the esophagus. "Hypermethylation of TMEM240 in 87.8% of CRC, 80.0% of esophageal cancer and 80.4% of liver cancer patients was reported in our previous study." (PMID 35715741, 2022).
inflammatory bowel disease (2 papers, 2020 to 2021). A spectrum of small and large bowel inflammatory diseases of unknown etiology. "Low expression of the TMEM240 protein was also observed in 50.0% of patients with inflammatory bowel diseases (IBDs)." (PMID 32398064, 2020).
liver cancer (2 papers, 2020 to 2022). An epithelial or non-epithelial malignant neoplasm that arises from the liver. "Interestingly, TMEM240 hypermethylation was also found in other cancers of the digestive system, such as esophageal and liver cancers." (PMID 32398064, 2020).
metastatic tumors (2 papers, 2020 to 2022). "TMEM240 protein expression was analyzed in 109 tumors from CRC patients, 32 CRC metastatic tumors from patients, 10 benign tumors, eight hyperplastic tumors, 10 colon tissues with inflammation, 11 adjacent normal tissues, and eight normal colon tissues by IHC." (PMID 32398064, 2020). "The TMEM240 protein level decreased in 91.7% (100/109) of tumors from CRC patients and in 75.0% (24/32) of the metastatic tumors from CRC patients but exhibited higher expression in 75.0% (6/8) of the normal colon tissues." (PMID 32398064, 2020).
breast tumors (1 paper, 2022). "Hypermethylation of TMEM240 was found in breast tumors of patients who displayed poor treatment response, especially in tumors from patients who received hormone therapy." (PMID 35715741, 2022). "The exon 1 region of TMEM240 was hypermethylated in 40.3% (251/623) of the breast tumor tissues." (PMID 35715741, 2022). "No local distribution of CNVs in the TMEM240 gene was found in breast tumors from patients." (PMID 35715741, 2022). "However, GISTIC2.0 analysis found no local distribution of CNVs in the TMEM240 gene in breast tumors from patients." (PMID 35715741, 2022).
colon cancer (1 paper, 2020). "We further transfected with two si-TMEM240 (s50536) and si-TMEM240 (s50534) into the colon cancer cell line HCT116, respectively." (PMID 32398064, 2020). "The microscopy and SRB assays showed that both si-TMEM240 s50534 and s50536 could significantly induce colon cancer growth by 15.9- and 14.9-fold, respectively." (PMID 32398064, 2020).
colorectal tumor (1 paper, 2020). "Again, the exon 1 region of TMEM240 was hypermethylated in 314 colorectal tumor tissues." (PMID 32398064, 2020).
hepatocellular carcinoma (1 paper, 2020). A malignant tumor that arises from hepatocytes. "The identification of TMEM240 hypermethylation using Infinium HumanMethylation450 BeadChips was also reported in the US hepatocellular carcinoma patients." (PMID 32398064, 2020).
invasive ductal carcinoma (1 paper, 2022). "Hypermethylation of TMEM240 was associated with Asian, ER-negative, PR-negative and triple-negative breast cancer patients and patients with invasive ductal carcinoma (all p < 0.001)." (PMID 35715741, 2022).
triple-negative breast carcinoma (1 paper, 2022). An invasive breast carcinoma which is negative for expression of estrogen receptor (ER), progesterone receptor (PR), and human epidermal growth factor receptor 2 (HER2). "Almost all triple-negative breast cancer patients (95.7%, 22/23) displayed deficient TMEM240 protein expression." (PMID 35715741, 2022). "Almost all triple-negative breast cancer patients (95.7%, 22/23) had deficient TMEM240 protein expression." (PMID 35715741, 2022).
tubular adenoma (1 paper, 2020). A usually polypoid neoplasm arising from the glandular epithelium. "In addition, hypermethylation of TMEM240 was found in 55.6% of patients with polyp tubular adenomas, supporting hypermethylation of TMEM240 as an early-onset indicator of CRC." (PMID 32398064, 2020).
α-synucleinopathy (1 paper, 2024). "Hub genes of the α-synucleinopathy-associated modules included RBP4, C1orf70 (TMEM240), and SCARF2, which have been previously implicated in PD." (PMID 38995454, 2024).
cancer (6 papers, 2020 to 2025). A tumor composed of atypical neoplastic, often pleomorphic cells that invade other tissues. "Multivariate Cox proportional hazards regression analysis found that mRNA expression of TMEM240 was significantly associated with overall, cancer-specific, and recurrence-free survival (p = 0.012, 0.007, and 0.022, respectively)." (PMID 32398064, 2020). "The membrane protein TMEM240 also negatively regulated several extracellular and membrane proteins involved in cell proliferation, migration, and cancer EMT, such as SDF-1, FGF2, oncostatin M, and MMP2." (PMID 35715741, 2022). "Overexpression of TMEM240 in T47D cells induced 76.9% cancer cell death when the cells were treated with 20 μM tamoxifen but only a 46.0% decrease in the vector control cancer cells when treated with 20 μM tamoxifen." (PMID 35715741, 2022). "Only in patients in which TMEM240 was expressed at sufficient levels in the cancer cells did hormone therapy produce a good therapeutic response." (PMID 35715741, 2022). "According to the cell viability sulforhodamine B (SRB) assay, the growth of DLD-1 cancer cells with TMEM240 was slow down by 66.6% compared to that of the vector control group." (PMID 32398064, 2020). "The proliferation of T47D (ER + /PR +) cells was significantly decreased by 62.9% when cells transfected with si-control were treated with 20 μM tamoxifen (p = 0.003), but only a 31.1% decrease in proliferation was observed in cancer cells transfected with si-TMEM240." (PMID 35715741, 2022). "Although hypermethylation of TMEM240 also occurs in other types of cancer, its high alteration in cancers may assist the detection of disease progression." (PMID 35715741, 2022). "The data showed that TMEM240 could lead to G1 cell cycle arrest, repress cancer cell proliferation, and inhibit cancer cell migration." (PMID 32398064, 2020). "According to the SRB cell viability assay, TMEM240 inhibited MDA-MB-231 and T47D cancer cell growth by 55.2% and 48.7%, respectively." (PMID 35715741, 2022). "Additionally, comparable to hypermethylation of RASSF1, hypermethylation of TMEM240 and DHRS3 have been described in several types of cancers, and these genes have been proposed as tumour suppressor genes." (PMID 39589853, 2025). "To date, the role of TMEM240 in cancer pathogenicity has not been completely elucidated." (PMID 34638449, 2021).
tumor (6 papers, 2020 to 2025). "Performance metrics such as sensitivity, specificity, and accuracy were averaged to ensure robustness, supporting the use of combined GCM2 and TMEM240 for monitoring treatment response and tumor burden." (PMID 40691650, 2025). "A Cox proportional hazards survival analysis further adjusted for race, age, tumor type, tumor stage and menopausal state showed that TMEM240 promoter hypermethylation was significantly and independently associated with 10-year overall survival (p = 0.002)." (PMID 35715741, 2022). "Analysis of RNA sequencing data from TCGA showed that TMEM240 mRNA expression was markedly significantly reduced in 41 paired CRC tumor tissues compared to the matched normal colorectal tissues (p = 0.019)." (PMID 32398064, 2020). "The data indicated that in 87.8% (480/547) of Taiwanese CRC patients, the methylation level of TMEM240 was at least 5-fold higher in tumor tissues than in the matched normal colorectal tissues." (PMID 32398064, 2020). "In 72.0% (85/118) of tissue samples, TMEM240 mRNA expression was lower in Taiwanese CRC tumor tissues than in normal colorectal tissues." (PMID 32398064, 2020). "In 72.0% (85/118) of tissue samples, TMEM240 mRNA expression was lower in Taiwanese CRC tumor tissues than in normal colorectal tissues according to real-time reverse transcription PCR results, and this was also found in benign tubular adenomas (44.4%)." (PMID 32398064, 2020). "TMEM240 was found to have tumor suppressor potential via affecting CRC cell growth and migration and was found to be hypermethylated in both Taiwanese and Western CRC patients." (PMID 32398064, 2020). "Hypermethylation of TMEM240 in tumor tissues was increased compared to normal tissues." (PMID 34638449, 2021). "A QMSP confirmed TMEM240 hypermethylation in CRC tumor tissues compared to normal tissues." (PMID 32398064, 2020). "We observed that the TMEM240 protein was mainly expressed in the plasma membranes of the cells of the normal colon mucosa but was deficiently or weakly expressed in the cytoplasm and nuclei of malignant CRC tumor cells." (PMID 32398064, 2020). "Using the TCGA data from colon, rectal, gastric cancer patients and their own results of the Illumina Methylation 450K BeadChip array analysis of a CRC patient tumor and normal tissues, the authors selected EHD3, TMEM240, and SMAD3 as promising tumor markers." (PMID 37569782, 2023). "In the Asian and TCGA cohorts, hypermethylation of the promoter region of TMEM240 in more than 80% of tumors was consistently found regardless of age, sex, tumor type, stage, tumor size, regional lymph node metastasis, or distant metastasis." (PMID 32398064, 2020).
benign tumors (1 paper, 2020). "Note that positive TMEM240 protein staining was detected in 87.5% (7/8) and 70% (7/10) of the hyperplastic colon tumors and benign tumors, respectively." (PMID 32398064, 2020).
gastrointestinal tract cancer (1 paper, 2020). "In addition to its use in CRC, TMEM240 hypermethylation may also be an early-onset indicator in gastrointestinal tract cancer." (PMID 32398064, 2020).
TMEM240 also shares sentences with these, for which no sentence is quoted: gastric cancer (2 papers); Spinocerebellar ataxia 21 (2); Ataxia (1); autosomal dominant spinocerebellar ataxia (1); Cognitive impairment (1); Dystonia (1); hyperkinetic disorders (1); movement disorder (1); myoclonic dystonia (1); Myoclonus (1); neurological disorder (1); pancreatic cancer (1); rectal cancer (1); uterine cancer (1).